FLT3LG (fms related receptor tyrosine kinase 3 ligand)
Diseases named in the same sentence as FLT3LG in open-access papers (continued):
Sharing a sentence is not in itself a finding about the gene and the disease.
tumor (continued). "Bioinformatics analysis revealed that the transcription level of FLT3LG was negatively correlated with the tumor purity of BLCA during tumor development." (PMID 38213738, 2024). "Clinical experiments have demonstrated that FLT3LG can increase the number of DCs in vivo and increase the proportion of tumor antigen specific CD8+ T cells." (PMID 38213738, 2024). "On the second day after BCG treatment, we collected tumor tissues and analyzed the changes in FLT3LG levels and tumor immune activation levels." (PMID 38213738, 2024). "The results showed that 10 ng/ml FLT3LG activated tumor-derived CD8+ T cells, leading to an increase in Cd25 transcription levels after 18 hours of stimulation." (PMID 38213738, 2024). "In vitro experiments showed that FLT3LG can synergize with T-cell receptor activators to promote the activation of tumor-derived T cells." (PMID 38213738, 2024). "The information above suggests that FLT3LG is likely involved in the regulation of the tumor immune response in BLCA." (PMID 38213738, 2024). "Another tumor-infiltrating XCL1high NK subcluster that expressed a high level of genes associated with the recruitment of DCs (XCL1, XCL2, and FLT3LG) was more highly detected in the PD-1+SMI than in the PD-1 group." (PMID 37430270, 2023). "NK cells promoted immune control of tumours by upping the intensity of the orthodox type-1 dendritic cells (cDC1s) in tumours via two cytokines'—FLT3LG and CCL-5—production, as per recent studies." (PMID 34336101, 2021). "FLT3LG expression and NK cell abundance in the tumor are correlated with increased cDC1 levels, better overall survival, and increased responses to anti-PD-1 immunotherapy in metastatic melanoma patients." (PMID 33613552, 2020). "In a mouse model, overexpression of FLT3LG in mice subjected to subcutaneous graft tumor elicited a pronounced immune response and could enhance the efficacy of anti-PD-1 therapy." (PMID 40329265, 2025). "The findings revealed that the overexpression of FLT3LG in tumor cells effectively impeded tumor growth, augmented the proliferation of CD4+ and CD8+ T cells, suppressed the activity of Treg cells, and significantly potentiated the efficacy of anti-PD-1 therapy." (PMID 40329265, 2025). "Specifically, we focused on examining the correlation of FLT3LG with immune cell infiltration and further explored the impact of FLT3LG overexpression on the efficacy of anti-PD-1 immunotherapy in LUAD by establishing a subcutaneous tumor model of LLC cells in mice." (PMID 40329265, 2025). "In contrast, five tumor types presented higher FLT3LG expression than normal tissues did." (PMID 40329265, 2025). "Transcriptional levels of FLT3LG were significantly increased within the tumor tissue." (PMID 38213738, 2024). "This information suggests that tumor-derived CD8+ T cells can be directly activated by FLT3LG." (PMID 38213738, 2024). "In addition, we found that with the evolution of tumor cell status, the expression levels of FLT3LG, GALNT10, IL1B, and IMPDH1 remained stable while ISG20 gradually increased." (PMID 36816023, 2023). "Tumor infiltration in Bruch’s membrane, an extracellular matrix between the retinal pigment epithelium and the choroid, showed a positive correlation with FLT3LG and MCP-1 (in aqueous and vitreous humor), and IL-8, IP-10, MIP-1α, and PDGF-AA (in vitreous humor)." (PMID 37628989, 2023). "Furthermore, in LUAD, FLT3LG expression was found to impact the penetration of immune cells in the tumor microenvironment and the overall quantity of immune cells, and these findings suggest that FLT3LG expression has the potential to increase the efficacy of anti-PD-1 immunotherapy." (PMID 40329265, 2025). "In addition, when we divided serum FLT3LG expression into high and low groups according to the median FLT3LG level, we detected a significant positive correlation between serum FLT3LG expression and PD-L1 expression in tumor samples from LUAD patients (P < 0.001)." (PMID 40329265, 2025).
tumor (continued). "Moreover, when verifying the effect of FLT3LG on LUAD in vivo, because we were conducting only a preliminary exploration, we focused solely on the overexpression of Flt3l in tumor cells, aiming to elucidate the influence of FLT3LG on LUAD and immunotherapy under conditions of heightened expression." (PMID 40329265, 2025). "The issue of whether the elevated Flt3Lg plasma level is a direct outcome of the reduced tumor mass and the reduced amount of Flt3Lg consumed by blast cells or Flt3Lg playing some crucial yet unknown function during therapy is of considerable importance but lies beyond of the scope of this work." (PMID 37108788, 2023). "However, dimeric Flt3Lg binds to the Flt3 receptor, forming a high-affinity homodimeric receptor complex that triggers intracellular proliferative signaling, thus acting as an undesirable tumor growth factor." (PMID 37108788, 2023). "Through in vitro and in vivo experiments, we disclosed that NCD upregulates the TIME-GES genes CXCL10, CXCL11, EBI3, and FLT3LG, promotes CD8+ T cell activation and tumor infiltration, thereby inhibiting the growth of TNBC." (PMID 41293150, 2025). "This inhibition promotes the secretion of immune-modulatory factors CXCL10, CXCL11, EBI3, and FLT3LG by tumor cells, thereby alleviating immunosuppression and enhancing CD8+ T cell recruitment into the tumor microenvironment and boosting antitumor immunity." (PMID 41293150, 2025). "Tumor dimensions exhibited strong correlations with IP-10 and MIP-1 in both aqueous and vitreous humor, but Fms-related tyrosine kinase 3 ligand (FLT3LG), IL-6, IL-8, and MCP-1 showed positive relationships solely in vitreous humor." (PMID 39596556, 2024). "Tumor-derived CD8+ T cells were sorted and treated with FLT3LG, CD3 antibody (αCD3), or their combination to analyze the phenotypic changes in T cells." (PMID 38213738, 2024). "Tumor dimensions showed positive correlations with IP-10, and MIP-1 (in aqueous and vitreous humor), while Fms-related tyrosine kinase 3 ligand (FLT3LG), IL-6, IL-8, and MCP-1 were positively correlated in vitreous humor." (PMID 37628989, 2023). "characterized “tumor-matching” T cells in the peripheral blood (i.e., T cells in the blood expressing tumor-specific TCRs) as cells that expressed a more effector phenotype with a decreased expression of genes GYPC, CCR7, LTB, and FLT3LG." (PMID 37122719, 2023). "Admittedly, FLT3LG has been shown to bind to FLT3 (receptor) on DCs to stimulate their differentiation and expansion, facilitating tumor antigen cross-presentation and anticancer immune responses." (PMID 36081495, 2022). "On the basis of the present data, the potential of FLT3LG to augment the effectiveness of anti-PD-1 therapy may be attributed to the promotion of immune cell proliferation and infiltration in TME (tumor microenvironment), with a particular emphasis on T cells." (PMID 40329265, 2025). "A positive correlation was observed between FLT3LG and MCP-1 (in aqueous and vitreous humor) and IL-8, IP-10, MIP-1α, and PDGF-AA (in vitreous humor) in the context of tumor infiltration in Bruch’s membrane, an extracellular matrix that lies between the retinal pigment epithelium and the choroid." (PMID 39596556, 2024). "The results showed that the expression levels of FLT3LG, GALNT10, IL1B, IMPDH1 and ISG20 were higher in tumor cells than in normal cells, while the remaining genes could not be identified because of the low expression levels in tumor cells." (PMID 36816023, 2023). "Considering FLT3LG is positively correlated with immune activity in the TME, this might be one of the reasons for the attenuated power of DCs in tumor antigen presentation." (PMID 36081495, 2022). "Examples include RIVAL 01/TBio-6517, a Vaccinia virus for tumor-directed expression of FLT3L, anti-CTLA-4, and IL-12 (NCT04301011), and ONCR-177 (NCT04348916), an HSV-1 mediating expression of IL-12, FLT3LG, CCL4, anti-PD-1, and anti-CTLA-4 to enhance induction of tumor-specific adaptive immunity." (PMID 33863363, 2021).
tumor (continued). "However, our results show that, along with the increase in FLT3LG, the levels of DCs did not significantly increase during BCG treatment, which may be due to tumor heterogeneity." (PMID 38213738, 2024).
cancer (57 papers, 2011 to 2026). A tumor composed of atypical neoplastic, often pleomorphic cells that invade other tissues. "We found that the FLT3LG exGS was largely explained by trans-pQTL that lie in established cancer risk genes involved in the regulation of cell division and DNA repair (CHEK2 [22:28695868:AG:A], ATM [11:108267276:T:C], and TERT [5:1293971:C:T])." (PMID 38750076, 2024). "The beneficial effect of FLT3LG in stimulating dendritic cells, enhancing cancer sensitivity to immunotherapy has been demonstrated." (PMID 40072746, 2025). "The T cell markers CD28 and FLT3LG expression decreased in cancer while FOXP3, IDO1, and ULBP2 expression increased." (PMID 39672307, 2024). "We found that individuals with cancer had lower levels of FLT3LG expression, indicating decreased activity of dendritic cells and T-cells." (PMID 39672307, 2024). "The expression of CD28 decreased in both cancer and precancer compared to the control group, while the expression of FLT3LG was decreased in cancer compared to precancer and controls." (PMID 39672307, 2024). "Moreover, we found downregulation of cancer-associated genes such as BCL2, FLT3LG, or PIK3r5 in cells treated with decitabine." (PMID 27658391, 2016). "Genes such FAM182A, SOX9, AHNAK2, ENSG00000121031, FLT3LG, PMEPA1, ZFP36L2 in the large intestine, ALB, KRTAP19-1, APOB, CD200, CRYGD, KRTAP24-1, OR6N2 in the liver are novel predictions, and their functions in these cancers can further be studied." (PMID 34997044, 2022). "Moreover, FLT3LG and CCL5 or CCR5 gene expression signatures correlate with an enhanced cDC1 signature and a favorable overall survival in patients with cancer." (PMID 33980589, 2021). "In the TCGA cohort, individuals with higher CD28 and individuals with higher FLT3LG expression had higher survival than those with lower CD28 expression and those with lower FLT3LG expression, showing that less immunosuppressed individuals were better able to combat cancer." (PMID 39672307, 2024).
hematological disease (2 papers, 2013 to 2022). "Previous reports have suggested that plasma levels of FLT3LG can be used as predictor of hematological disease in GATA2 deficiency, and used in clinical monitoring post-HSCT." (PMID 34893945, 2022).
FLT3LG also shares sentences with these, for which no sentence is quoted: infection (38 papers); COVID-19 (18); breast carcinoma (10); Sepsis (10); lymphoma (9); Arthritis (6); rheumatoid arthritis (6); colorectal cancer (5); malaria (5); atherosclerosis (4); colitis (4); lupus (4); asthma (3); bacterial infections (3); colon carcinoma (3); myeloproliferative disease (3); neutropenia (3); non-small cell lung carcinoma (3); Obesity (3); ovarian carcinoma (3); allergic asthma (2); brain tumor (2); cardiovascular disease (2); endometriosis (2); endothelial dysfunction (2); gout (2); hepatoma (2); hyperlipidemia (2); inflammation (2); Lymphadenopathy (2).
A further 102 diseases each share a sentence with FLT3LG in 2 papers or fewer.